PPARGC1A (PPARG coactivator 1 alpha)
Diseases named in the same sentence as PPARGC1A in open-access papers (continued):
Sharing a sentence is not in itself a finding about the gene and the disease.
tumor (continued). "This suggests that the expression levels of HSPA1A and PPARGC1A might have a specific impact on the behavior and function of immune B cells in the tumor microenvironment of HCC." (PMID 37993485, 2023). "It was predicted that the genes such as FOXM1 and MYBL2 were activated while HNF4A and PPARGC1A were inhibited in tumor cells, which drove liver tumor, digestive organ tumor, abdominal neoplasm, tumorigenesis of tissue, neoplasia of cells and oxidation of lipid." (PMID 36212481, 2022). "Moreover, PPARGC1A levels are already elevated in samples from patient OAC tumours containing high ERBB2 levels compared to the precursor Barrett’s oesophagus." (PMID 36153371, 2022). "We recently reported that PPARGC1A expression is progressively silenced with RCC tumor progression." (PMID 34609963, 2021). "Moreover, PPARGC1A, the gene encoding PGC1-α protein, a regulator of OXPHOS metabolism, was significantly overexpressed in circulating tumor cells, and the suppression of PGC1-α markedly weakened the stemness features of CSCs." (PMID 34451892, 2021). "Four genes (MRPL54, ZC3H13, IFIT5, and PPARGC1A) were downregulated and may function as tumor suppressor genes in HCC, and showed a positive correlation with prognosis." (PMID 33251144, 2020). "In addition, slight but statistically significant correlations were found between PPARGC1A and stemness indices and tumor purity." (PMID 33029111, 2020). "Interestingly, PPARGC1A expression wasdifferentially affected within our tumor sample of the same histopathologicalentity." (PMID 25791281, 2015). "PPARGC1A may play a protective role in limiting tumor progression by regulating mast cell status." (PMID 40564032, 2025). "However, there are few studies on the role of PPARGC1A expression in tumor immunity." (PMID 34702278, 2021). "We observed an increase of Ppargc1a mRNA levels of 13-fold in the gastrocnemius, a muscle composed of similar levels of Type I (oxidative) and Type II (glycolytic) fibers and 19-fold in the quadriceps, a muscle composed mostly of Type II fibers, in 4-month-old tumor-free transgenic MCK-PGC-1α mice." (PMID 22428048, 2012). "In this study, FABP4, PPARGC1A, AGPAT4, ALDH1A1, and GPAT3 were identified as downregulated tumor suppressor genes in TC, whereas TGFA was recognized as an oncogene." (PMID 40119647, 2025). "The RT-qPCR analysis revealed significantly decreased expression of ESR1, APOA1, IGF1, PPARGC1A, SERPINE1 and PON1 in tumor tissues compared with adjacent normal tissues (P < 0.05)." (PMID 40317014, 2025). "PPARGC1A, also known as PGC-α, regulates tumor metabolism and suppresses the metastasis of HCC cells by inhibiting the Warburg effect." (PMID 38694506, 2024). "miR-23a then directly targets and reduces the expression of PGC1A (encoding PPARG coactivator 1 alpha) and G6PC (encoding glucose-6-phosphatase), leading to a decrease in glucose production, which might ultimately contribute to the survival of tumor cells under hypoxic conditions." (PMID 38172648, 2024). "Compared to the normal tissue in the TCGA cohort, ACOX2 (P < 0.001), PTGS1 (P < 0.001), PTGS2 (P < 0.001), and PPARGC1A (P < 0.001) were downregulated, while HAO1 (P < 0.001) was upregulated in tumor samples." (PMID 38706909, 2024). "A significant increase in UCK2, HMMR, and MAGEA6 expression and a significant decrease in CXCL8, EPO, PPARGC1A, FTCD, and CFHR3 expression was observed in tumor tissues." (PMID 38694506, 2024). "TRAP1 and P4HA1 are highly expressed at the intracellular level, whereas PPARGC1A, EFHD1, and HIGD1A are only expressed by a minority of tumor cells." (PMID 37903487, 2024).
tumor (continued). "Compared to those in normal tissues, APOE, STEAP4, and C1QTNF3 expressions were upregulated in tumor tissues, whereas BNIP3L and PPARGC1A expressions were downregulated." (PMID 39524226, 2024). "HIGD1A, EFHD1, and PPARGC1A were found to be overexpressed in normal tissue, whereas TRAP1 and P4HA1 were found to be overexpressed in CRC tumor tissue (p < .001)." (PMID 37903487, 2024). "The master regulator of mitochondrial biogenesis, PPARG, as well as PPARGC1A and the downstream effectors and transcription factors NRF1 and BACH1, are upregulated in various metastases as compared to the primary tumor or to the target site." (PMID 38039408, 2023). "Compared with normal liver tissue, the expression of PPARGC1A in HCC tissue is downregulated and acted as a tumor inhibitory role in the occurrence and development of HCC69." (PMID 37903974, 2023). "CD36 can also participate in tumor pathogenesis by regulating the PPAR pathway and inhibiting the mitochondrial biogenesis regulator gene PPARGC1A." (PMID 36591255, 2022). "Some downregulated genes were considered to function as tumor suppressor genes, such as PPARGC1A, also known as PGC-1α, a master regulator of mitochondrial biogenesis and oxidative phosphorylation." (PMID 34660596, 2021). "To confirm the involvement of PPARδ in regulating CPT1A, we showed that treating PT130 cells or Apc/Kras tumor organoids with PPARδ agonist GW501516 directly stimulated the expression of CPT1A and PPARGC1A (a known PPARδ target gene)." (PMID 32913185, 2020). "Significant differences were found between PPARGC1A and PPARGC1B towards their relationship with tumor purity." (PMID 33029111, 2020). "Ppargc1α controls mitochondrial function, oxidative phosphorylation, and reactive oxygen-specific detoxification, and enforced expression of PGC-1α in tumor-specific CD8+ T cells has been shown to render them more metabolically active and to enhance cytotoxicity." (PMID 41373645, 2025). "We performed multidimensional analyses on PPARA, PPARG, PPARD, PPARGC1A, and PPARGC1B, including differential expression analysis in pan-cancer, immune subtype analysis, clinical analysis, tumor purity analysis, stemness correlation analysis, and drug responses." (PMID 33029111, 2020). "The result showed that five genes (PRKCA, ADORA1, PPARGC1A, KL, GNG7) could be identified as potentially prognostic factors, and they have also been suggested as tumor suppressor genes." (PMID 31661791, 2019). "Importantly, decreased levels of mitophagy-related BNIP3L and PINK1, as well as increased levels of mitochondrial biogenesis related genes PPARGC1A and PPARGC1B were found in the basal-like tumor samples when compared to the Luminal A subtype." (PMID 31231612, 2019). "Among 6 significant hub genes, significantly decreased AGPAT9, AQP7, HMGCS2, KLF15, PPARGC1A mRNA expressions were found in ccRCC tissues compared with adjacent normal tissues, while MLXIPL mRNA expression was significantly elevated in tumor samples compared with normal samples." (PMID 31493764, 2019). "Meanwhile, the negative correlation between PPARGC1A and activated mast cells suggests that it may attenuate the pro-inflammatory effects of mast cells in the tumor microenvironment by inhibiting their activation." (PMID 40564032, 2025). "The high positive correlation between the expression of HSPA1A and PPARGC1A genes and the infiltration of nTreg cells, B cells, macrophages, and monocytes in TCGA-LIHC suggests a potential role for these genes in regulating immune cell infiltration within the tumor microenvironment of HCC." (PMID 37993485, 2023). "Moreover, according to the C1-C6 immune subtypes previously identified by investigators, we classified tumor samples by representative immune signatures and examined the RNA-seq level of PPARA, PPARD, PPARG, PPARGC1A, and PPARGC1B from C1 to C6, which were all seen to have differential expressions." (PMID 33029111, 2020).
cancer (387 papers, 2006 to 2026). A tumor composed of atypical neoplastic, often pleomorphic cells that invade other tissues. "To accomplish this, we measured cancer growth, survival, and apoptosis using different apoptotic markers in PPARGC1A-deficient (siPPARGC1A and SR-18292 treatment) FaDu-MOCK or FaDu-CLU cells during cisplatin treatment." (PMID 38447939, 2024). "Both increased and decreased PPARGC1A expression have been reported in a range of cancer types and associated with a worse prognosis." (PMID 35625955, 2022). "PPARGC1A (PGC1α) is emerging as a potential target for cancer treatment due to its functional role being closely linked to cancer development, chemoresistance, and distant metastasis." (PMID 33917757, 2021). "A strong association between the metastatic potential of cancer cells and the transcriptional co-activator PGC-1α (PPARGC1A) has been reported." (PMID 40422220, 2025). "After 3 days, we observed that all five cancer cell lines that were co-cultured with UCP1, PPARGC1A or PRDM16 CRISPRa-treated human adipocytes showed significantly lower cell numbers than cancer cells co-cultured with dCas9–VP64-treated adipocytes." (PMID 39905264, 2025). "PPARGC1A positively regulates cancer growth metastasis, but inhibition significantly reduces mitochondrial number, cell proliferation, and survival against ROS-driven apoptosis in cancer cells." (PMID 38447939, 2024). "The expression of TRAP1 in pan‐cancer was shown to be substantially inversely linked with that of HIGD1A and EFHD1, and positively correlated with that of PPARGC1A, according to a correlation study of 5 MRGs." (PMID 37903487, 2024). "No significant PDAC-related changes were detected in the expression of Ppargc1a, the role of which in metabolism and prognosis of cancer cachexia is still controversial." (PMID 36979889, 2023). "To gain mechanistic insight, we followed up on prior reports that invasive cancer cells use the transcriptional coactivator PPARGC1A (PGC-1α) to enhance oxidative phosphorylation and mitochondrial biogenesis." (PMID 38039408, 2023). "Invasive cancer cells use the transcription coactivator peroxisome proliferator-activated receptor γ, coactivator 1α (PPARGC1A, PGC-1α) to enhance the oxygen consumption rate, oxidative phosphorylation, and mitochondrial biogenesis." (PMID 38039408, 2023). "Further, the prognostic direction of these frequent top NMF genes was consistent across the five-cancer group, with the exception of PPARGC1A." (PMID 37973839, 2023). "This is consistent with our findings of significantly earlier cancer development in carriers with mutations in both PPARGC1A and BRCA1/2, as well as lower PPARGC1A expression in the PPARGC1A mutation carriers." (PMID 35625955, 2022). "Increased expression and activity of PPARGC1A in cancers of lung, prostate, cervical, breast, colon, and melanoma promoted cancer cell progression and chemoresistance." (PMID 36587194, 2022). "These contradicting observations are now thought to result from cancer cells exploiting PPARGC1A to provide them metabolic plasticity to support their evolving needs along the course of cancer development." (PMID 35625955, 2022). "There are studies reported that miR-93 can promote different cancer cells proliferation, migration and progression by targeting PPARGC1A 24, PTEN 25, RB1 26, TIMP2 27, and so on." (PMID 31737116, 2019). "Two cancers (#615 and #3008) had acquired homozygous deletions at the CDKN2A locus (chr9p21.3), and other homozygous deletions present in single cancers involved genes such as PPARGC1A, RFX3 and FAT1." (PMID 24777035, 2014). "We altered PPARGC1A expression and investigated its effects on cancer aggressiveness." (PMID 39085357, 2024). "Ppargc1a/Esrra axis has been extensively studied in cancer and established as a central regulatory node of energy metabolism that induces the global expression of genes involved in mitochondrial biogenesis and functions (Ranhotra, 2010; Deblois and Giguère, 2011; Ranhotra, 2012)." (PMID 39269443, 2024).
cancer (continued). "In the context of SI-NET and IBD, such metabolism was mainly performed through glycolysis as per the Warburg effect, a phenomenon in which cancer cells prefer glycolysis over oxidative phosphorylation (regulated by PPARGC1A) to produce glucose, even in the context of ample oxygen." (PMID 39233736, 2024). "The Ppargc1a/Esrra axis has not previously been implicated in tolerization but has been extensively studied in cancer, underscoring the novelty of our findings." (PMID 39269443, 2024). "During early tumorigenesis, PPARGC1A may be downregulated to facilitate the increased consumption of glucose and glutamine in cancer cells." (PMID 35625955, 2022). "Given the impact of PPARGC1A on the age of onset of OC and BC among BRCA mutation carriers, our results could have significant implications for cancer risk prediction and personalized preventive care for BRCA carriers." (PMID 35625955, 2022). "This chromatin remodelling revealed that the HNF4A and PPARGC1A regulated transcriptional regulatory networks play a pivotal role in promoting the emergence of drug resistant cancer cells and represent potential therapeutic targets to enhance the efficacy of ERBB2 inhibition strategies." (PMID 36153371, 2022). "Also, PPARGC1A (q-value = 1.49−03, log2FC = 1.48), a protein involved in cancer metabolic adaptation to stress, was upregulated." (PMID 36551516, 2022). "Similarly, upstream PPARGC1A is used by invasive cancer cells to enhance oxidative phosphorylation, oxygen consumption rate, and mitochondrial biogenesis." (PMID 33937086, 2021). "Methylation in PPARGC1A gene was reported to predict cancer incidence." (PMID 33632303, 2021). "Interestingly, we examined expression of PPARGC1A in a broader panel of PCa cell lines in the Broad Cancer Cell Line Encyclopedia98, which revealed that in seven out of eight models the expression was downregulated by more than two Z-scores." (PMID 33230156, 2020). "Using MEXPRESS, we specifically examined the correlation between methylation at the cg11270806 probe (located at the -816-position relative to the PPARGC1A transcription start site, being the nearest probe to the -783 CpG site) with PPARGC1A expression in different cancer types." (PMID 32933059, 2020). "We also manually checked the literature for Ppargc1a transcriptional targets as this PI gene had increased expression in the KO, finding a study that identified binding sites within the promoter regions of 558 genes in the human liver HepG2 cancer cell line." (PMID 33330474, 2020). "It is plausible that PPARGC1A may play a larger role in eliciting metformin’s anti-cancer effects than our predictions suggest, owing to the constraining set of differentially expressed genes we used when generating the sub-networks." (PMID 26841718, 2016). "The PPI network identified that ESRRG was significantly related to 20 genes, including PPARGC1A, PPARGC1B, MED1, CREBCF and so on, 6 of which were confirmed to be positively correlated with ESRRG expression by the XenaShiny TCGA Association Analysis module for single cancer." (PMID 40356747, 2025). "Normal B and cancer 1 clusters shared inflammatory markers CCL2, TNFRSF12A, and IL1R1, pathways including TNFα, IL, and Myc signaling, and activity of inflammation, hypoxia, and lipid metabolism–associated transcription factors NFATC2, ARNT, PPARA, and PPARGC1A." (PMID 40215177, 2025). "Inhibition of Esrra has also been shown in cancer cell metabolism studies to interfere with pyruvate entry in mitochondria by inhibiting the expression of Mpc1, and inhibition of Esrra led to decreased expression of Ppargc1a-controlled expression of mitochondrial genes in mice brains." (PMID 39269443, 2024).
cancer (continued). "We found that the interaction between PPARGC1A mutation status and BRCA status significantly associated with an earlier age of cancer onset (p = 0.03), while the main effect of each gene alone was not significant (p = 0.33 and 0.96, respectively, for PPARGC1A status and BRCA status)." (PMID 35625955, 2022). "Peroxisome proliferator-activated receptor gamma, coactivator 1 alpha (PPARGC1A) was reported to promote metastasis through mediating mitochondrial biogenesis and oxidative phosphorylation in cancer cells." (PMID 36139663, 2022). "PPARGC1A, also known as PGC-1α, functions as a master regulator of mitochondrial biogenesis and oxidative phosphorylation and plays a pivotal role in cancer cell metabolism and metastasis." (PMID 33251144, 2020). "Peroxisome proliferator-activated receptor gamma coactivator-1 alpha (PPARGC1A) is suggested to be involved in generation of a number of disorders, particularly cancer." (PMID 32612456, 2020). "The expression patterns of PPARA (p < 0.001), PPARD (p < 0.001), PPARG (p < 0.001), PPARGC1A (p < 0.001), and PPARGC1B (p < 0.001) varied in 6 immune subtypes in pan-cancers." (PMID 33029111, 2020). "For example, LeBleu and co-workers identified the transcription coactivator peroxisome proliferator-activated receptor gamma, coactivator 1alpha (PPARGC1A or PGC-1α) as the transcription factor promoting mitochondrial biogenesis and OXPHOS in cancer cells." (PMID 26812134, 2016). "These adaptations were not due to alterations in mitochondrial mass, with only a modest increase in TOMM20 protein upon cancer regardless of temperature (+15%), accompanied by a decreasing trend of Tfam and Ppargc1a." (PMID 40237521, 2025). "Further investigations are required to figure out the potentials of PPARs and their coactivators as drug targets for cancer, which makes our study even more important in the contribution to the expression signature analysis of PPARA, PPARD, PPARG, PPARGC1A, and PPARGC1B." (PMID 33029111, 2020). "In both cases, PPARGC1A-dependent metabolic reprogramming is elicited following inhibition of either a RTK (MET) or a downstream pathway component (BRaf), demonstrating a common response to RTK pathway inhibition in rewiring metabolic programmes in OAC and these cancers." (PMID 36153371, 2022). "The PPARGC1A mutations we identified through WGS were dominantly non-coding variants, which highlights the importance of going beyond just the gene coding regions in search of BRCA modifiers and cancer predisposition genes." (PMID 35625955, 2022). "A small number of hypoxia-associated genes (APLN, HIF1A, and BNIP3), cancer stem cell (CSC) markers (CD24 and CD44), hormonal regulation (HR) genes (ESR1, PGR, and TFF1), other selected genes (PPARGC1A, ILK), and HKGs (RPL32, GUSB, TBP, OAZ1 and NONO) were also included in the panel." (PMID 34206049, 2021). "The role of PPARGC1A methylation in cancer has not been studied." (PMID 29361779, 2018).